UGT1A1 (UDP glucuronosyltransferase family 1 member A1)
Description:
[Isoform 1]: UDP-glucuronosyltransferase (UGT) that catalyzes phase II biotransformation reactions in which lipophilic substrates are conjugated with glucuronic acid to increase the metabolite's water solubility, thereby facilitating excretion into either the urine or bile. Essential for the elimination and detoxification of drugs, xenobiotics and endogenous compounds. Catalyzes the glucuronidation of endogenous estrogen hormones such as estradiol, estrone and estriol. Involved in the glucuronidation of bilirubin, a degradation product occurring in the normal catabolic pathway that breaks down heme in vertebrates. Involved in the glucuronidation of arachidonic acid (AA) and AA-derived eicosanoids including 15-HETE, 20-HETE, PGB1 and F2-isoprostane (8-iso-PGF2alpha). Involved in the glucuronidation of the phytochemical ferulic acid at the phenolic or the carboxylic acid group. Also catalyzes the glucuronidation the isoflavones genistein, daidzein, glycitein, formononetin, biochanin A and prunetin, which are phytoestrogens with anticancer and cardiovascular properties. Involved in the glucuronidation of the AGTR1 angiotensin receptor antagonist losartan, a drug which can inhibit the effect of angiotensin II. Involved in the biotransformation of 7-ethyl-10-hydroxycamptothecin (SN-38), the pharmacologically active metabolite of the anticancer drug irinotecan. [Isoform 2]: Lacks UGT glucuronidation activity but acts as a negative regulator of isoform 1.
Synonyms: hUG-BR1; UDPGT 1-1; GNT1; UGT1; UGT1A; BILIQTL1; UDPGT
Tractability: Small molecule: a high-quality ligand is known. Antibody: UniProt predicts a signal peptide or a membrane-spanning region; its Gene Ontology location is reachable by antibodies, with medium confidence. PROTAC: its protein half-life has been measured; a small molecule that binds it is known.
Target class: Enzyme; Transferase
Safety:
Unwanted effects reported when the protein is acted on. In parentheses: how it was acted on, where the effect was seen, and who reports it.
diarrhea (source: ClinPGx)
fatigue (source: ClinPGx)
hyperbilirubinemia (source: ClinPGx)
liver failure (source: ClinPGx)
nephrolithiasis (source: ClinPGx)
neutropenia (source: ClinPGx)
neutropenia or discontinuation due to adverse events (source: ClinPGx)
thrombocytopenia (source: ClinPGx)
Gene: Protein-coding gene on chromosome 2 (233,760,270 to 233,773,300, forward strand). Ensembl gene ENSG00000241635.
Subcellular location: Endoplasmic reticulum membrane; Cytoplasm, perinuclear region
Pathways (Reactome):
Drug ADME: Aspirin ADME; Paracetamol ADME
Metabolism: Glucuronidation; Heme degradation
Disease: Defective UGT1A1 causes hyperbilirubinemia
Gene Ontology:
Molecular function: enzyme binding; enzyme inhibitor activity; glucuronosyltransferase activity; protein binding; protein homodimerization activity; retinoic acid binding; steroid binding; protein heterodimerization activity; UDP-glycosyltransferase activity
Biological process: bilirubin conjugation; estrogen metabolic process; flavone metabolic process; flavonoid metabolic process; heme catabolic process; xenobiotic metabolic process; cellular response to glucocorticoid stimulus; glucuronate metabolic process; liver development; negative regulation of steroid metabolic process; retinoic acid metabolic process; steroid metabolic process; monocarboxylic acid metabolic process
Cellular component: endoplasmic reticulum; endoplasmic reticulum membrane; endoplasmic reticulum chaperone complex; endoplasmic reticulum lumen; perinuclear region of cytoplasm; plasma membrane
Genetic constraint (gnomAD): Loss-of-function variants: 33 observed, 42.44 expected, observed/expected ratio (o/e) 0.78, 90% interval 0.59 to 1.04. The upper end of that interval is the gene's LOEUF score, 1.04, which puts it in group 4 of 6, group 1 being the genes least tolerant of losing a copy. Missense variants: 694 observed, 707.57 expected, observed/expected ratio (o/e) 0.98, 90% interval 0.92 to 1.04. Synonymous variants: 249 observed, 280.88 expected, observed/expected ratio (o/e) 0.89, 90% interval 0.8 to 0.99.
Homologues: Orthologues: macaque UGT1A1 (95% identical), rat Ugt1a5 (79% identical), mouse Ugt1a1 (79% identical), tropical clawed frog ugt1a1 (60% identical), zebrafish ugt1a1 (52% identical), tropical clawed frog ugt1a6 (50% identical), Caenorhabditis elegans ugt-62 (28% identical), Caenorhabditis elegans ugt-61 (28% identical), Drosophila melanogaster Ugt302C1 (27% identical), Drosophila melanogaster Ugt35B1 (26% identical), Drosophila melanogaster Ugt302E1 (26% identical), Drosophila melanogaster Ugt35A1 (26% identical), and 79 more. Paralogues in human: UGT1A5 (73% identical), UGT1A3 (72% identical), UGT1A4 (72% identical), UGT1A6 (69% identical), UGT1A9 (67% identical), UGT1A10 (67% identical), UGT1A8 (67% identical), UGT1A7 (66% identical), UGT2B4 (44% identical), UGT2B10 (44% identical), UGT2A2 (43% identical), UGT2B17 (43% identical), and 9 more.
Diseases named in the same sentence as UGT1A1 in open-access papers:
UGT1A1 is named in the same sentence as 204 diseases in open-access papers, as found by Europe PMC text mining. Sharing a sentence is not in itself a finding about the gene and the disease. The quoted sentences say what the papers report.
Hyperbilirubinemia (200 papers, 2008 to 2026). An increased amount of bilirubin in the blood. "Pharmacogenetic analyses have implicated uridine diphosphate glucuronosyltransferase 1A1 (UGT1A1) polymorphisms in nilotinib-induced hyperbilirubinemia, consistent with previous reports of TKI-associated hepatotoxicity." (PMID 40978483, 2025). "Enasidenib, acting both as a substrate and inhibitor of UGT1A1, is associated with hyperbilirubinemia due to off-target inhibition of the UGT1A1 enzyme (14% overall; 8% grade 3–4)." (PMID 40183077, 2025). "In fact, genotyping in the seven subjects with an elevation of indirect bilirubin of >3.0 mg/dL in the current study showed a polymorphism (UGT1A1*28) associated with benign indirect hyperbilirubinemia in Gilbert’s Syndrome in six of these subjects." (PMID 40969937, 2025). "Gilbert syndrome (GS) is an inherited disorder characterised by unconjugated hyperbilirubinemia due to a deficiency in hepatic UDP-glucuronosyltransferase 1A1 (UGT1A1) enzyme activity, responsible for bilirubin glucuronidation." (PMID 39996891, 2025). "In contrast, other hypomorphic variants in the UGT1A1 gene lead to moderate reductions in glucuronidation activity and mild hyperbilirubinemia characteristic of GS." (PMID 40243597, 2025). "Neonatal hyperbilirubinemia, which is often linked to UGT1A1 and G6PD variants, is highly prevalent in China, affecting approximately 34.4% of full-term neonates and is generally considered treatable." (PMID 40421383, 2025). "Gilbert’s syndrome, a polymorphism in the UGT1A1 promoter (UGT1A1*28) that reduces its expression by ~50% and affects nearly 10% of the human population, is the most common hereditary cause of hyperbilirubinemia." (PMID 39873298, 2025). "Mutations in the UGT1A1 locus therefore can cause several diseases associated with hyperbilirubinemia or the build-up of bilirubin." (PMID 38474028, 2024). "Previous case reports have demonstrated that the coexistence of multiple UGT1A1 gene variants can cause a cumulative effect on the degree of hyperbilirubinemia by reducing expression of functional UGT1A1 enzyme." (PMID 39021718, 2024). "In the dominant model, UGT1A1-rs4148323 AA + GA genotypes were associated with an increased risk of hyperbilirubinemia (OR 2.768,p = 0.004)." (PMID 38279097, 2024). "Nilotinib is a common drug used in imatinib-resistant or imatinib-intolerant CML, and it is recommended to test for the genetic variant associated with nilotinib-induced hyperbilirubinemia, such as UGT1A1*28 and UGT1A1*6, ahead of nilotinib administration." (PMID 39065732, 2024). "Crigler–Najjar Syndrome (CNS) is a rare genetic disorder caused by mutations in the UGT1A1 gene, leading to impaired bilirubin conjugation and severe unconjugated hyperbilirubinemia." (PMID 39456788, 2024). "In the present study, our analysis confirmed the strong association between the UGT1A1 gene and hyperbilirubinemia, highlighting the effectiveness of GWASs in validating gene–disease associations." (PMID 39457450, 2024). "Gilbert syndrome is the most common hyperbilirubinemia, associated with a mutation in the UGT1A1 bilirubin gene, which produces an enzyme that conjugates bilirubin with glucuronic acid." (PMID 39064690, 2024). "Most studies highlight genetic polymorphisms as the cause to hyperbilirubinaemia, mostly with mutations involving UGT1A1 and SLCO1B1." (PMID 39609276, 2024). "Haplotype analysis showed the ACG haplotype of UGT1A1 were associated with an increased hyperbilirubinemia risk (OR 3.122, p = 0.001), whereas the GCG haplotype was related to a reduced risk (OR 0.523, p = 0.018)." (PMID 38279097, 2024). "In CNS1, there is a complete loss of UGT1A1 activity due to deletions, insertions, missense mutations, or premature stop codons, resulting in severe unconjugated hyperbilirubinemia." (PMID 39456788, 2024). "Gilbert syndrome is one type of hyperbilirubinemia caused by insertion mutations in the TATA-box of the UGT1A1 promoter." (PMID 38474028, 2024).
Hyperbilirubinemia (continued). "Our research indicated striking relationships between the vulnerability to severe hyperbilirubinemia and the gene polymorphisms for UGT1A1 and SLCO1B3." (PMID 38279097, 2024). "We aim to discuss the complexity of multiple UGT1A1 gene variants and its effect on the degree of observed hyperbilirubinemia." (PMID 39021718, 2024). "Pazopanib is a UGT1A1 inhibitor and especially patients with Gilbert syndrome, caused by a polymorphism in UGT1A1, have an increased risk of hyperbilirubinemia with the use of pazopanib." (PMID 38104304, 2024). "They suggested that breastfed infants with the UGT1A1 7/7 genotype are more susceptible to hyperbilirubinemia and very prolonged jaundice compared to formula-fed infants." (PMID 38334089, 2024). "A genetic deficiency or inhibition of UGT1A1 results in elevated serum bilirubin levels, leading to hyperbilirubinemia, commonly known as jaundice." (PMID 39457450, 2024). "Rats that had a loss-of-function mutation in their Ugt1a1 gene exhibited hyperbilirubinemia and were protected against hypertension and end-stage organ damage." (PMID 36671031, 2023). "Experimental studies in mice with the human Gilbert’s syndrome polymorphism (UGT1A1*28) were shown to have moderate hyperbilirubinemia and were protected from high-fat diet-induced hepatic steatosis (NAFLD) and insulin resistance." (PMID 36671031, 2023). "Individuals with the Gilbert’s syndrome polymorphism (UGT1A1*28) have reduced expression of the hepatic UGT1A1 enzyme, resulting in mild hyperbilirubinemia." (PMID 36830621, 2023). "UGT1A1*6 and *28, missense variants leading to reduced enzyme activity, showed clinical significance as pathogenic variants for a hyperbilirubinemia condition called Gilbert’s syndrome, which is associated with irinotecan toxicity in Asians." (PMID 37261288, 2023). "Although a consensus has been reached on the role of UGT1A1 polymorphisms in neonatal unconjugated hyperbilirubinemia, their association with SHB remains uncertain." (PMID 38274110, 2023). "Crigler-Najjar syndrome is a rare disorder of bilirubin metabolism caused by uridine diphosphate glucuronosyl transferase 1A1 (UGT1A1) mutations characterized by hyperbilirubinemia and jaundice." (PMID 36936447, 2023). "The presence of UGT1A1 211G>A mildly increased the risk of severe unconjugated hyperbilirubinemia caused by ABO/Rh incompatibility hemolysis (OR 3.98, 95% CI 2.19–7.23), although the effect is not statistically significant." (PMID 38274110, 2023). "The other study from Japan indicated that UGT1A1 211G>A served as a risk factor for neonatal hyperbilirubinemia only in infants with inadequate breastfeeding." (PMID 38274110, 2023). "Glucose-6-phosphate dehydrogenase (G6PD) deficiency and polymorphism in uridine diphosphate glucuronosyl transferase 1A1 (UGT1A1) were associated with significant neonatal hyperbilirubinemia (NHB) and increased risk for kernicterus." (PMID 37508669, 2023). "We have shown the efficacy of LNP-encapsulated mRNA for treating hyperbilirubinemia resulting from UGT1A1 deficiency in the Ugt1 KO mouse model of CN1." (PMID 36936447, 2023). "UGT1A1*6 appears to be a risk factor for prolonged jaundice with hyperbilirubinemia in term infants of Chinese ancestry who are exclusively breastfed." (PMID 36605758, 2022). "In this study found that all neonates carrying homozygous variant in UGT1A1*6 had high development of hyperbilirubinemia (5/5; 100%; P < 0.001)." (PMID 35501760, 2022). "More importantly, UGT1A1 mutation is a pathogenic risk factor for cholelithiasis, given that UGT1A1 defects lead to bile acid malabsorption accompanied by enhanced bilirubin uptake and the development of hyperbilirubinemia." (PMID 36128448, 2022). "This strong association of UGT1A1 exon mutation with neonatal hyperbilirubinemia remained statistically significantly after adjusting for known clinical risk factors for neonatal hyperbilirubinemia including gender, age and ethnic group." (PMID 36520959, 2022).
Hyperbilirubinemia (continued). "To study alternative bilirubin clearance pathways in vivo, we used a mouse strain with genetically induced hyperbilirubinemia due to a null mutation in the Ugt1a1 gene." (PMID 36142606, 2022). "Neonates carrying with homozygous (AA) and heterozygous (GA) variants in UGT1A1*6 were significantly related to hyperbilirubinemia development compared with wild type (GG; P < 0.001)." (PMID 35501760, 2022). "The compound heterozygous UGT1A1*6 and UGT1A1*28 are major genotypes associated with the high risks of hyperbilirubinemia in Chinese Han people." (PMID 36128448, 2022). "These mice lack functional Ugt1a1 protein and enzyme activity due to a targeted null mutation in Ugt1a exon 4, developing severe hyperbilirubinemia soon after birth." (PMID 36142606, 2022). "We were the first study to conduct on combined UGT1A1 variants and its effects on Thai neonatal hyperbilirubinemia." (PMID 35501760, 2022). "Innate ethnic variation in UGT1A1, which encoded for the key enzyme involved in the conjugation of bilirubin has been reported to contribute to the biologic basis of hyperbilirubinemia risk in Asian." (PMID 36520959, 2022). "Another variant is UGT1A1*6, 211G > A at exon 1, has been reported as a risk factor for neonatal hyperbilirubinemia in Asians." (PMID 35501760, 2022). "In conclusion, UGT1A1 promoter polymorphism seem to be an important genetic modulator of plasma bilirubin level and neonatal hyperbilirubinemia risk within ethnic groups." (PMID 36520959, 2022). "UGT1A1*6 polymorphism is frequent in neonates with severe hyperbilirubinemia in the Chaozhou region of southern China." (PMID 36128448, 2022). "This is the first study to investigate the potential reno-protective effects of endogenous mild unconjugated hyperbilirubinemia caused by hepatic UGT1A1 inhibition in a mouse model of CsA-induced kidney damage." (PMID 36295901, 2022). "Mutations in UGT1A1 cause the reduction of bilirubin conjugation, leading to hereditary unconjugated hyperbilirubinemia." (PMID 35415244, 2022). "The deficiency of UGT1A1 enzyme results in serve unconjugated hyperbilirubinemia, appearing to be a risk factor for gallstone formation in Jamaican patients with sickle cell disease." (PMID 36128448, 2022). "Previous studies focused on UGT1A1 polymorphisms and hyperbilirubinemia have reported results for Japanese patients with RA." (PMID 36675722, 2022). "Clinical data of Korean patients with hyperbilirubinemia showed that UGT1A1*27 allele was significantly different between patients and healthy individuals." (PMID 36128448, 2022). "A number of previous studies have shown that homozygous UGT1A1*28 and homozygous UGT1A1*6 are associated with an increased risk of hyperbilirubinemia." (PMID 35340156, 2022). "At the same time, patients with UGT1A1*6 mutations are also more prone to concurrent hyperbilirubinemia." (PMID 35340156, 2022). "Specifically, neonates who carried heterozygous or homozygous variation in the exon of UGT1A1 had a 2.21(95%CI:1.09–4.49) fold risk of hyperbilirubinemia as compared with those having the wild genotype (P = 0.03)." (PMID 36520959, 2022). "UGT1A1 mutations are the main pathogeneses of congenital hyperbilirubinemia, with G71R being the most common." (PMID 35415244, 2022). "Our results showed that combined UGT1A1*28 and *6 is a high-risk factor for developing neonatal hyperbilirubinemia." (PMID 35501760, 2022). "Since atazanavir inhibits the uridine diphosphate glucuronosyltransferase (UGT), responsible for bilirubin conjugation, patients living with HIV with the UGT1A1*28 allele present a high risk of hyperbilirubinemia." (PMID 35676899, 2022). "Genetic variation in UGT1A1 underlies the development of unconjugated hyperbilirubinemia that is a lithogenic risk factor for gallstone formation in multiple diseases, such as sickle cell disease, cystic fibrosis, and pigmentous gallstones." (PMID 36128448, 2022).